IL1A (interleukin 1 alpha)
Diseases named in the same sentence as IL1A in open-access papers (continued):
Sharing a sentence is not in itself a finding about the gene and the disease.
infection (continued). "Various inflammatory cytokines such as TNF (TNF), some ILs (IL1α, IL1β), and chemokines (including CCL2, CCL4, CCL5, CXCL8) were significantly up-regulated under all observation points after YC-2020 infection." (PMID 36338035, 2022). "Increased cytokines and chemokines such as IL-6, GM-CSF, IL-1a, IL-15, CXCL9 and CXCL10 and complement system components such as C3 were also observed from 6 to 36 months after infection in patients with chronic disease compared to with retrieved controls." (PMID 36189282, 2022). "The IAV single-infection group showed a rapid increase in the levels of TNF-α, IL-1α, IL-6, and IFN-β from 2 dpi to 7 dpi." (PMID 35107382, 2022). "After 2 h of infection, the transcriptional upstream regulators EGFR, EGR1, FOXL2, FOXO3, IL1A, IL1B and RELA were activated in MKN-28 cells infected with either H. pylori wt or the ΔhtrA mutant, while WWTR1 was inhibited." (PMID 37193047, 2022). "In control animals, we noted a significant increase in proinflammatory cytokines (IL-1α, IL-1β, IL-6, and TNF-α), and chemokines (RANTES/CCL5 and CXCL1) coupled with the surge of G-CSF in response to infection." (PMID 33514747, 2021). "Accordingly, gene expression analysis revealed an early and significant induction of IL1A, IL6, and CXCL8 expression during infection of keratinocytes with S. aureus accounting for the detrimental effects observed." (PMID 34944618, 2021). "After 1 day of infection, the oral tissues of the gefitinib-treated mice contained significantly less CXCL1/KC, CCL20, IL-1α, IL-1β, IL-17A, and the host defense peptide S100A8 than control mice." (PMID 33471869, 2021). "Infection with the als3Δ/Δ and ece1Δ/Δ single mutants induced significantly less secretion of CXCL8/IL-8, CCL20, IL-1α, and IL-1β than the wild-type parent strain." (PMID 33471869, 2021). "The percentages of IL-4+, IL-5+, IL-6+, IL-21+, IL-1α+, and IL-17+ γδT cells were increased (p < 0.05), but the percentage of IFN-γ-expressing γδT cells decreased (p < 0.05) post-infection." (PMID 33588839, 2021). "The lung and trachea homogenates from all animals had detectable cytokines (IL-6, IL-1α, IL-1β, TNFα and TGFβ) and chemokine (MCP-1) at Day 7 post-infection." (PMID 34452519, 2021). "Infection of BMDM with the Δami1 mutant induced a prominently proinflammatory cytokine response, through increased secretion of IL-1α, IL-6, and IL-12p40." (PMID 33980132, 2021). "For instance, serum and plasma from patients with a mild to moderate infection contained significantly greater levels of MCP-3, IL-1α, TNFβ, IL-4, IL-5, IL-6, IL-8, IL-9, and IL-13 compared to serum and plasma from patients that were critically ill." (PMID 34790978, 2021). "This is in line with our unpublished results, which demonstrate that ex vivo infection of vaginal explants with HSV-2 results in upregulation of not only IFN-λ but also several other immune factors, including CXCL9, CXCL10, IL-1α and TNF-α." (PMID 35126336, 2021). "Seven cytokines were identified as infection-specific, showing elevated concentrations in the septic TKR cohort compared to both the aseptic TKR and primary TKA cohorts: IL-1α, IL-1β, IL-6, IL-8, MCP-1, MIP-1α, and MIP-1β (p < 0.05)." (PMID 32867801, 2020). "Ms_YrbE3A infection resulted in the highest concentrations of pro-inflammatory cytokines, including TNF-α, IL-1β, IL-6, MCP-1, IL-1α, IL-12p70, and IFN-γ, in the lungs at 2 d PI and later decreasing rapidly from 4 to 21 d PI." (PMID 32316659, 2020). "infection, whereas the corresponding early responding genes in SCC cells were IL10, IL1β, IL1α, TNF, CXCL10, CXCL1, HBEGF, IL6, and CSF3." (PMID 31912662, 2020). "In contrast, the attenuated NH/P68 presented a higher sensitivity to classical and IFN-α activation, and infection resulted in downregulated expression of MHC class I in all the subsets and release of IL-1α, IL-1β, and IL-18 from moM1." (PMID 32178332, 2020).
infection (continued). "In agreement with the gene expression data, infection with Mtb WT significantly increased the secretion of IFN-α, TNF-α, IL-8, MCP-1, IL-1-α, IL-6 and MIP1-α and MIP1-β." (PMID 32938685, 2020). "Highly expression of the inflammatory factors from IL-1 family such as IL-1α, IL1-β, and IL-RN was found in C13-PD-L1+ (CD274+) neutrophils at the early stage of infection (day 1 p.i.)." (PMID 32101596, 2020). "After 2 h of infection with Mtb WT, there was a significant upregulation of immune modulators such as TNF, IL-1A, IL-1B and IL-6." (PMID 32938685, 2020). "Infection of the keratinocytes resulted in strong bacterial damage of HaCaT cells along with low cellular ATP levels and high release of LDH, IL-6, and IL-1α after 24 h and 48 h." (PMID 33302597, 2020). "Compared to ZIKV/Cambodia, the experimental infection of hiNPCs with ZIKV/Brazil resulted in a diminished induction of ISGs and lower induction of several cytokines (IFN-α, IL-1α/β, IL-6, IL-8, and IL-15), consequently favoring virus replication." (PMID 31474994, 2019). "Similar to WT mice, in the CNS of Rag1−/− mice IFN-α1, IFN-β, TNF, IL-1α, IL-1β, IL-6, and IFN-γ mRNA levels increased following i.c. infection with ZIKV, and IL-2, IL-3, IL-4, and IL-5 mRNA was not detectable (data not shown)." (PMID 31511023, 2019). "In contrast to infection of epithelial cells, infection of PMA-stimulated THP-1 cells resulted in increased production of CXCL1/Gro α, IL-1α, and IL-8 at 24 h post-infection while IL-6 was repressed by all serovars at this timepoint." (PMID 32039039, 2019). "In the CNS of WT mice, increased IFN-α1, IFN-β, TNF, IL-1α, IL-1β, IL-6, and IFN-γ mRNA levels were seen at day 4 post infection, and with the exception of IFN-α1, which decreased slightly, cytokine mRNA levels increased further by day 6 post infection." (PMID 31511023, 2019). "At day 6 post-infection, C57BL/6J mice also exhibited higher levels of IL1A, IL1B, CCL2, CCL3, IL2, IL10, and IL6." (PMID 30713529, 2018). "We found in spleens from BALB/c mice 2 days after infection significant amounts of IFN-γ, IL-1α, IL-1β, IL-10, IP-10, and MIG." (PMID 30500862, 2018). "In the context of TC-83 infection, we note that U-87 MG astrocytes produce increased levels of IL-1β, while HMC3 microglia release more IL-1α, IL-1β, IL-6, and IL-8." (PMID 30101649, 2018). "Specifically, pro-inflammatory cytokine (e.g. IL-1α, MIP, and TNFα) levels rise, enhancing neutrophils migration to the infection site." (PMID 29117213, 2017). "Compared to 129sv mice, the levels of TNF-α, IL-1α, and MIP-1α were 76%, 58%, and 42% higher in Alox5−/− mice at the 1st day post-infection." (PMID 29247243, 2017). "After 4 days of infection, the rBCG-CMX and BCG vaccines induced greater IL-1α production than the saline group." (PMID 28446902, 2017). "We found that the levels of IL-1α, INF-γ, TNF-α, MCP-1, IL-1β, IL-10, IL-6, IL-27, and IL-17α in the lungs post infection were significantly different between alcohol- and pair-fed mice." (PMID 28604843, 2017). "In different time-points, the infection of 129sv mice was characterized by significant neutrophil recruitment, oedema formation, and the production of TNF-α, MIP-1α, IL-1α, MCP-1, LTB4, PGE2, and α-defensin-1 in the lungs." (PMID 29247243, 2017). ", 2005), interleukin (IL)‐1α, IL‐6, tumor necrosis factor (TNF)‐α, and interferon (IFN)‐γ levels were significantly upregulated upon infection of ND mice, as were many others." (PMID 27794208, 2017). "We found that the levels of IL-1α, INF-γ, TNF-α, MCP-1, and IL-6 in the lungs post infection were significantly different between mice recolonized with microbiota from alcohol-fed and pair-fed microbiota." (PMID 28604843, 2017). "Interleukin gene activation was limited to IL1A, IL1B, IL7, and IL15 at 6 h, followed by a downregulated expression of all genes, except IL7, at 16 h of infection." (PMID 28993767, 2017).
infection (continued). "At the 1st and 3rd day, infection with A. xylosoxidans induced significant release of TNF-α, MIP-1α, IL-1α and MCP-1 in both 129sv and Alox5−/− mice." (PMID 29247243, 2017). "We also detected increased levels for IL-1α, IL-4, IL-10 and M-CSF, implying that these cytokines, along with IL-12 and INF-γ, play important roles in controlling the infection and confining the chronic infection in inactive state." (PMID 27895319, 2016). "On counter with such antigens, the complex interaction of antigen presenting cells, T cells and inflammatory mediators like IL1α, IL1β, TNFα, IL12, IL18 and IL23 lead to proinflammatory immune response and further clearance of infection." (PMID 27301453, 2016). "In our study, we evaluated cytokines produced in both the acute (IL-1α/β and TNF-α) and the chronic phases (IFN-γ, IL-10, and IL-6) of inflammation/infection and involved in the bone remodeling (IL-6)." (PMID 27478310, 2016). "As HBECs are the primary source of IL-1α, we initially characterized the response of fully differentiated primary HBECs to HRV16 infection." (PMID 27583193, 2016). "Similar to the data generated with PA01, infection of PLEC with 4616 at 105 cfu/mL induced cell injury, some cell death, and IL‐1α release at 12 h." (PMID 26714197, 2016). "The inflammatory markers IL-6, IL-1α and IL1-β were expressed at similar levels in both infections at early times, while TNFα was preferentially present in S. mitis infections." (PMID 26171605, 2015). "The expression level of some proinflammatory molecules (e.g., CCR5, CXCR4, IL1A, IL1R1, IL8, and TNF) peaked on day 3 or 6 following infection." (PMID 25719526, 2015). "Homogenates of kidneys from CD11cΔSyk mice showed higher levels of IL-6, KC, MIP-1α, IL-1β, TNF, IL-1α and MCP-3 at days 1 or 2 post-infection when compared to control mice." (PMID 25033445, 2014). "Here, in vitro infection showed that both isolates induced a strong production of NO and the cytokines TNF-α, IL-6, IL-1α, IL-1β, and IL-10." (PMID 24886263, 2014). "In contrast, we observed significantly less production of IL-12p40, IL-12p70, IL-1α, IL-1β, IL-17A, CXCL1, CCL2 and CCL5 in the lungs as the infection progressed." (PMID 25119981, 2014). "However, presence of either IL-1α or IL-1β in single-deficient mice is sufficient to control acute M. tuberculosis infection, with restrained bacterial burden and lung pathology, in conditions where TNF deficient mice succumbed within 4 weeks with overwhelming infection." (PMID 25400917, 2013). "In this study, analysis from C. trachomatis infected macrophages revealed increased levels of GM-CSF, IL-1α, IL-1β, IL-6, TNF, IL-12p70, and IL-10 after a 2-day infection, with TNF, IL-6, and IL-1α being more robustly produced." (PMID 23766556, 2013). "Here, we further analysed the respective roles of IL-1α and IL-1β, as compared with TNF in host response to infection by virulent M. tuberculosis but also attenuated M. bovis BCG." (PMID 25400917, 2013). "At both 17 and 48 hours after infection, 12 cytokines were elevated (G-CSF, M-CSF, IFN-γ, IL-1α, IL-1β, IL-12p70, IL-15, IL-17A, IP-10, MCP-1, MIG, and MIP-1α) in infected mice compared to placebo-inoculated mice." (PMID 23520553, 2013). "Collectively, our data indicate that L. pneumophila triggers caspase-11 activation and IL-1α release independently of the ASC and NLRC4 inflammasomes during both in vitro and in vivo infection." (PMID 23762026, 2013). "We find significantly altered innate antiviral responses in pregnant mice, including decreased levels of IFN-β, IL-1α, and IFN-γ at early time points of infection." (PMID 22792357, 2012). "Rather, RTD-1 administration appeared to protect infected animals by reducing pulmonary inflammation and suppressing IL-1α, IL-1β, IL-6, IL-12, CXCL1 (KC), CCL2 (MCP-1), CCL3 (MIP-1α), and CCL5 (RANTES) 2–4 days post-infection." (PMID 23236475, 2012).
infection (continued). "In contrast, there was a greater activation of genes such as TNF-α, IL1A, IL8, JUN, ERRFI1 and KLF6 after infection with N. lactamica relative to N. meningitidis." (PMID 22028815, 2011). "In the first, immune response genes such as IL-6, IL-1α, IL-1β and IFN-β were upregulated one hour following infection but this upregulation rapidly returned to baseline and was not sustained." (PMID 21789257, 2011). "At the higher inoculum, WT and tlr4 mutant mice exhibited significantly increased levels of IL-1α, IFN-γ, TNF-α, MCP-1, IL-1β, IL-6, and IL-17A early during infection relative to the lower inoculum while levels dissipated by 7 dpi, consistent with bacterial clearance." (PMID 40817088, 2025). "Levels of IL-1α in bladders were not significantly impacted by catheterization, infection, or E64 treatment; however, E64 treatment of CAUTI mice was associated with higher levels of G-CSF." (PMID 40980878, 2025). "Later during infection, however, tlr4 mutant mice had elevated, albeit not significantly higher, amounts of TNF-α, IL-1α, and IL-6 relative to WT mice, consistent with persistent infection." (PMID 40817088, 2025). "Supporting this, whilst both Il1a and Il1b gene expression were increased in LPS-RSV mice on day 1 post infection, only IL-1α and not IL-1β protein was detectable in the airways." (PMID 39127259, 2024). "Neither the CD8α nor the IL-1α treated mice lost weight or had changes in food consumption following infection." (PMID 38382577, 2024). "The DEGs involved in cytokine signaling were upregulated following infection with RHDV2 and included inflammatory cytokines such as IL1α, IL-6, and IL-8, and chemokines such as CCL2, CXCL9, and CXCL11, which were significantly upregulated compared with the non-infected rabbits." (PMID 38675838, 2024). "To confirm the increase of Th17 cells observed in IL-1α + OmpX vaccinated mice was not due to infection, we also performed ELISpot on lung cells isolated from uninfected immunized or PBS-treated mice." (PMID 38594380, 2024). "Indeed, compared to HC and IPF patients (which again overall behaved similarly), M-COV1/2 PBMCs secreted, upon infection with live PAO1, less IL-8, MIP-1α, IL-1α, IL-1b, TNF-α, G-CSF, MIP-2α, IL-23 and IL-10." (PMID 38835759, 2024). "Furthermore, we observed a significant increase in TNFα, IL-1α, IL-2, IL-3, IL-4, IL-9, IL-10, IL-12 (P70), IL-17A, and CCL5 on day 4 post-infection in murine macrophages." (PMID 39038037, 2024). "Trends for P80-mediated drop in inflammatory processes during infection were further visible for IL-6 and IL-1α (pink and yellow bar charts), though these were not significant." (PMID 38419061, 2024). "As expected, the Il1aΔ559,1 mice had no detectable IL-1α in the serum prior to infection, and a small, though not statistically significant, increase 24 h after infection." (PMID 38594380, 2024). "During PRRSV infection, activated alveolar macrophages and other inflammatory cells secrete proinflammatory cytokines such as TNF-α, IL-1α/β, IL-6, IL-8, and IL-12, as well as TGF-β, to recruit neutrophils and lymphocytes to the site of infection and facilitate pathogen clearance." (PMID 38806818, 2024). "This is not the first report of IL-1α and IL-1β seemingly having differential roles during infection." (PMID 39127259, 2024). "Notably, infection with a swine H3N2 isolate prompted increased IL-6 and IL-1α protein secretion compared to a seasonal human H3N2 virus." (PMID 38179335, 2023). "In addition to the robust release of pulmonary IL-6 and G-CSF, similar to infection with chs3Δ, YNB-U-grown cells also induced the expression of additional inflammatory molecules such as IL-1α, TNF-α, and the CCL class of chemokines." (PMID 37538303, 2023). "Furthermore, significant variations were observed in the levels of IFNL1, IL1A, IL6, and CCL2 interferons or other cytokines in cell supernatant through ELISA when comparing these two infection conditions." (PMID 37515115, 2023).
infection (continued). "In SARS-CoV-2 infection, regardless of infection severity, both IL-1α and IL-1β have high values, contributing to triggering cytokine storms and uncontrolled immune responses." (PMID 37510190, 2023). "Research revealed that NHDF cell lines do not produce IL-1α either in control conditions or during infection with C. albicans." (PMID 36835379, 2023). "Therefore, this study aims to analyze the efficacy of LL-37 cream in enhancing wound healing rate, decreasing the levels of IL-1α, TNF-α, and altering the pattern and number of aerobic bacteria colonization in DFU with mild infection." (PMID 37480520, 2023). "In contrast, USUV infection induced significantly greater upregulation of CCL2 and IL1α." (PMID 36495563, 2023). "Other inflammatory makers, including IL-1α, IL-1β and IL-6, were not different between infection groups." (PMID 36748431, 2023). "In conclusion, LL-37 cream enhanced the healing rate of DFU with mild infection, but did not decrease the levels of IL-1α and TNF-α and the number of aerobic bacteria colonization." (PMID 37480520, 2023). "Surprisingly, there were no increases in the levels of either IL-1α or IL-1β after infection with the virulent isolate SY18 or its attenuated derived mutant, SY18ΔL7-11." (PMID 36680273, 2023). "However, IPA identified pro-inflammatory upstream regulators including PTGS2 (COX2), IL1A, and TNF that were activated after infection in aged mice." (PMID 35614490, 2022). "In addition, inflammation-related genes including NLRP3, IFI16, IL6, IL1A, CXCL2, and CCL6 were upregulated, further confirming that infection by T. gondii induces a robust immune response to limit infection." (PMID 35012632, 2022). "In contrast, moM1 infection with virulent 22653/14 ASFV did not induce the release of either proinflammatory (IL-1α, IL-1β, IL-6, TNF-α) or anti-inflammatory (IL-10) or pro-Th1 (IL-12, IL-18) cytokines." (PMID 35215216, 2022). "S. oralis infections as single species caused a significant increase in the expression of IL-1α, IL-6, IL-12 (p40), CXCL1/KC, CCL5/RANTES, and CCL11 compared to infection without implants." (PMID 35203495, 2022). "2-methylpentane was only detected in amniotic fluids after infection with Up and not in IL-1α induced CA." (PMID 34368028, 2021). "On Day 4 post-infection there were no or very low detectable levels of systemic IL-6, IL-1α or IL-1β in the Group 3.2 animals." (PMID 34452519, 2021). "In particular, TLR3 might act via IRF3, producing interleukin (IL)-1α, IL-1β, IL-4, IL-6, and IFN-α and IFN-β, during the first 24 h post-infection." (PMID 34576716, 2021). "IL-1α, IL-1β, MIP-1α, and tumor necrosis factor alpha (TNF-α) were reduced in both IAV- and mock-infected animals at 24 h pbi during infection with each SGD mutant compared to their levels during infection with WT D39 (P < 0.05), except for D39ΔpurD in mock-infected animals (P > 0.05)." (PMID 33875471, 2021). "By contrast, IL-6 and IL-1α were significantly induced after Mb, but not Mtb, infection, and IL-8 production was also significantly higher after Mb than Mtb infection." (PMID 34307535, 2021). "The constitutively expressed cytokines IL-1α and TNF-α were elevated already in early stages of the infection, whereby TRP was able to significantly reduce their gene expression 24 h and 48 h post infection." (PMID 32024909, 2020). "Infection with RV1b increased IL-1α in non-CF (61.6 ± 31.7 pg/mL vs. 511 ± 252 pg/mL; p < 0.05) and CF AEC supernatant compared to controls (46.2 ± 32.7 pg/mL vs. 236 ± 93.1 pg/mL; p < 0.05)." (PMID 32328066, 2020). "To address this, we infected mice lacking either IL-1α or IL-1β and analyzed the cellular immune response and parasite burden during chronic phase of infection." (PMID 32703941, 2020). "Interestingly, cells infected with MDR-PA also induced significantly higher expression of IL-1α in CHME-3 cells at 4 h and 6 h post-infection." (PMID 32423093, 2020).